ENSG00000289517 (novel protein)
Gene: Protein-coding gene on chromosome 22 (42,583,836 to 42,627,688, reverse strand). Ensembl gene ENSG00000289517.
Genetic constraint (gnomAD): Missense variants: 214 observed, 192.92 expected, observed/expected ratio (o/e) 1.11, 90% interval 0.99 to 1.24. Synonymous variants: 75 observed, 74.66 expected, observed/expected ratio (o/e) 1, 90% interval 0.83 to 1.22.